RPL36AL (ribosomal protein L36a like)
Synonyms: RPL36A; RPL36AP42; RPL36A_18_1363
Tractability: Antibody: its Gene Ontology location is reachable by antibodies, with high confidence; the Human Protein Atlas places it where antibodies can reach. PROTAC: ubiquitination databases record sites on it; its protein half-life has been measured.
Gene: Protein-coding gene on chromosome 14 (49,618,530 to 49,620,649, reverse strand). Ensembl gene ENSG00000165502.
Subcellular location: Cytoplasm
Subcellular location (Human Protein Atlas): Cytosol; Endoplasmic reticulum; Plasma membrane
Pathways (Reactome):
Metabolism of proteins: Eukaryotic Translation Termination; Formation of a pool of free 40S subunits; GTP hydrolysis and joining of the 60S ribosomal subunit; L13a-mediated translational silencing of Ceruloplasmin expression; PELO:HBS1L and ABCE1 dissociate a ribosome on a non-stop mRNA; Peptide chain elongation; Ribosome Quality Control (RQC) complex extracts and degrades nascent peptide; SRP-dependent cotranslational protein targeting to membrane; ZNF598 and the Ribosome-associated Quality Trigger (RQT) complex dissociate a ribosome stalled on a no-go mRNA
Metabolism of RNA: Major pathway of rRNA processing in the nucleolus and cytosol; Nonsense Mediated Decay (NMD) enhanced by the Exon Junction Complex (EJC); Nonsense Mediated Decay (NMD) independent of the Exon Junction Complex (EJC)
Cellular responses to stimuli: Response of EIF2AK4 (GCN2) to amino acid deficiency
Developmental Biology: Regulation of expression of SLITs and ROBOs
Disease: Viral mRNA Translation
Metabolism: Selenocysteine synthesis
Gene Ontology:
Molecular function: protein binding; structural constituent of ribosome
Biological process: cytoplasmic translation; translation
Cellular component: nucleus; cytosolic large ribosomal subunit; cytoplasm; ribosome
Genetic constraint (gnomAD): Loss-of-function variants: 8 observed, 8.31 expected, observed/expected ratio (o/e) 0.96, 90% interval 0.56 to 1.67. That is too few expected variants to judge how well the gene tolerates losing a copy. Missense variants: 76 observed, 130.35 expected, observed/expected ratio (o/e) 0.58, 90% interval 0.48 to 0.71. Synonymous variants: 44 observed, 45.94 expected, observed/expected ratio (o/e) 0.96, 90% interval 0.75 to 1.23.
Homologues: Orthologues: macaque RPL36AL (99% identical), rabbit RPL36A (99% identical), zebrafish rpl36a (97% identical), mouse Gm6525 (94% identical). Paralogues in human: RPL36A (99% identical).
Diseases named in the same sentence as RPL36AL in open-access papers:
RPL36AL is named in the same sentence as 7 diseases in open-access papers, as found by Europe PMC text mining. Sharing a sentence is not in itself a finding about the gene and the disease. The quoted sentences say what the papers report.
Alzheimer disease (3 papers, 2022). A progressive, neurodegenerative disease characterized by loss of function and death of nerve cells in several areas of the brain leading to loss of cognitive function such as memory and language. "Studies have found that Rpl36al may serve as a diagnostic biomarker based on immune infiltrates in Alzheimer’s disease." (PMID 36569748, 2022).
RPL36AL also shares sentences with these, for which no sentence is quoted: breast carcinoma (1 paper); cancer (1); cardiovascular disease (1); diabetes mellitus (1); hepatoma (1); tauopathy (1).